FASN (fatty acid synthase)
Diseases named in the same sentence as FASN in open-access papers (continued):
Sharing a sentence is not in itself a finding about the gene and the disease.
colorectal cancer (continued). "Accordingly, genetic knock-down of FASN upregulated CD36 and lipid uptake in colorectal cancer, but not in OC cells." (PMID 33928023, 2021). "In contrast to a very recent report in colorectal cancer, we demonstrate in OC cells (A2780, OVCAR3, SKOV3) that neither FASN inhibitors (G28UCM, Fasnall) nor FASN-specific siRNAs can stimulate a relief pathway leading to enhanced uptake of extrinsic FAs or low density lipoproteins (LDLs)." (PMID 33928023, 2021). "In addition to PKM2, PFKFB3, and FASN, there are no available reports about the role of HMGCS2 and angiogenesis in various cancers, including colorectal cancer." (PMID 31355161, 2019).
lung carcinoma (86 papers, 2006 to 2026). "High FASN expression was closely associated with decreased survival and increased cell proliferation and invasion in lung cancer." (PMID 39478862, 2024). "A recent work showed that FASN overexpression was associated with poor prognosis of several types of cancer, such as ovarian, lung cancer and gastric cancer." (PMID 37124526, 2023). "The upregulation of FASN in lung cancer has been associated with the overexpression of B7-H3, a glycoprotein with immunoregulatory functions identified as a predictor of poor survival in NSCLC patients." (PMID 35159223, 2022). "Subsequent studies in EGFR mutated non‐small cell lung cancer confirmed that FASN-associated fatty acid metabolic pathway upregulation was the main principal for tyrosine kinase inhibitor (TKI)‐resistant EGFR mutated NSCLC growth." (PMID 35898882, 2022). "The present study demonstrates that FASN deficiency clearly inhibits the malignant phenotypes of lung cancer cells in vivo and in vitro." (PMID 31122252, 2019). "ATP citrate lyase and FASN upregulation has been shown in colorectal, gastric, liver, and lung cancer, and their overexpression has been significantly associated with poor survival in lung cancer patients." (PMID 38874588, 2024). "ACLY and FASN upregulation has been shown in colorectal, gastric, breast, liver, and lung cancer, and their overexpression has been significantly associated with poor survival in lung cancer patients." (PMID 35159223, 2022). "FASN is strongly associated to poor prognosis and resistance to treatment in different human tumors such as breast, bladder, pancreatic, or lung cancer." (PMID 32438613, 2020). "Moreover, by analyzing TCGA datasets and online microarray data, we confirmed the overexpression of FASN in lung cancer and its association with poor prognosis." (PMID 29722168, 2018). "However, there are also successful cases, such as the up-regulation of FASN expression in lung cancer, which is associated with poor prognosis, and inhibitors targeting FASN, such as orlistat, can inhibit tumor growth by preventing EGFR palmitoylation and enhancing its ubiquitination." (PMID 41281744, 2025). "The maximum reduction in tumor weight in response to TVB-3664 treatment achieved in our study was 50% which is significantly less than the >80% reduction in tumor growth in non-small-cell lung cancer PDXs treated with TVB-3166 suggesting that lung cancer may be more susceptible to FASN inhibition." (PMID 29872506, 2018). "Studies on lung cancer cells have shown that MAPK1 phosphorylation inhibits FASN expression, while MAPK1 activation enhances the expression of fatty acid metabolism genes such as CPT1a in diabetic cardiomyopathy." (PMID 41010281, 2025). "B7-H3 overexpression in lung cancer leads to abnormal lipid metabolism through the SREBP-1/FASN axis, resulting in poor prognosis of lung cancer." (PMID 40625923, 2025). "MiR-320 can directly target fatty acid synthase (FASN) to restrain lung cancer growth via interfering with fatty acid metabolism." (PMID 38341418, 2024). "Orlistat, a FASN inhibitor, has been shown to impair tumor cell proliferation and metastasis in several cancers, including colon, prostate, and lung cancer 9-14." (PMID 37283794, 2023). "Pharmacological inhibitors of FASN inhibit lung cancer cell survival, induce programmed cell death, and reduce lung cancer xenograft tumor growth." (PMID 38069382, 2023). "We generated FASN-overexpressing and knockdown cell lines from A549 cells, a human lung cancer cell line." (PMID 37270622, 2023). "The effect of de novo lipogenesis on lipid remodeling has also been studied using KRAS-mutant lung cancer cells after fatty acid synthase (FASN) inhibition." (PMID 37612411, 2023). "For instance, stimulation of the TGFβ signaling pathway in lung cancer cells decreases fatty acid production by inhibiting ChREBP, and knockdown of FASN decreases E-cadherin expression, which increases lung cancer cell invasion and metastasis." (PMID 37993654, 2023).
lung carcinoma (continued). "In human lung cancer patients, overexpression of ACLY and FASN in tumor tissues are observed and associated with a poor post-treatment survival rate." (PMID 38069382, 2023). "EGCG also reduced FASN and free fatty acid levels in lung cancer cells at the same time as inhibiting fatty acid synthesis without affecting protein expression in lung cancer xenograft tumors." (PMID 35243817, 2022). "Inhibition of FASN by cerulenin blocked proliferation of KRAS-driven lung cancer cells, indicating a promising role of lipid metabolism in tumor treatment." (PMID 35898882, 2022). "In this study, we also investigated the correlations between 35 polymorphisms in 9 DNA repair genes (XRCC3, BRCA2/ZAR1L, XPC, RAD52, MAD2L2, NFKB1, NFKBIA, TNFRSF1A, and FASN) with platinum-based chemotherapy prognosis in 399 patients with lung cancer." (PMID 35899106, 2022). "Several studies reported that increased levels of FASN expression are detectable early during the development of lung cancer, particularly in patients with a prolonged history of smoking, and are correlated with aggressiveness in stage I lung carcinomas." (PMID 35159223, 2022). "De novo synthesis is the main pathway for cancer cells to produce fatty acids (FAs); FA synthase (FASN) is highly expressed in various cancers including lung cancer and low production of FASN in NSCLC patients have longer survival." (PMID 34620841, 2021). "For instance, a high expression of fatty acid synthase and stearoyl CoA desaturase 1 (SCD1) is associated with relatively high risk of lung carcinoma and with poor patient prognosis." (PMID 33467111, 2021). "KRAS can also induce fatty acid synthase (FASN) to promote lipogenesis, and inhibition of FASN was shown to block cellular proliferation of KRAS-mutant lung cancer cells." (PMID 34947990, 2021). "Through sterol regulatory element-binding protein (SREBP), B7-H3 has been reported to regulate the fatty acid synthase (FASN) gene, thus exerting effects on lipids in lung cancer." (PMID 32477326, 2020). "Then, another study on lung cancer cell lines showed that FASN can promote TGFβ signaling, thus reinforcing the EMT process." (PMID 32932943, 2020). "FASN is highly expressed in many types of lung cancers; thus, its stabilization by SUMO underscores a possible mechanism of upregulating fatty-acid synthesis by SUMOylation as part of the oncogenic process." (PMID 32781719, 2020). "In this study, we revealed the role of FASN in mediating EMT/metastasis increase in cisplatin-resistant lung cancer, which will have great clinical significance as increased invasive features of cisplatin-resistance cells have been reported." (PMID 27765901, 2016). "Taken together, we suggest that targeting the FASN molecule or TGF-β1 signaling would inhibit EMT/metastasis of cisplatin-resistant lung cancer." (PMID 27765901, 2016). "This is a novel, interesting discovery and indicates a critical implication of the FASN-TGFβ1-FASN feedback loop in mediating EMT/metastasis increase in cisplatin-resistant lung cancer." (PMID 27765901, 2016). "In mechanism dissection studies, we investigated which molecule is the FASN downstream molecule that can mediate EMT/metastasis increase in cisplatin-resistant lung cancer cells." (PMID 27765901, 2016). "Fatty acid synthase (FASN), a multifunctional enzyme playing a key role in biosynthesis of FA, is up-regulated in prostate, breast, and lung carcinomas." (PMID 22886728, 2013). "Numerous studies have demonstrated high levels of FASN expression in various malignant and pre-malignant lesions, including lung carcinomas." (PMID 22886728, 2013). "This is the first evidence that EGFR is involved in the regulation of FASN expression in a lung cancer model with EGFR-overexpression." (PMID 22769244, 2012). "Fatty acid synthase (FASN) is overexpressed and hyperactivated in several human carcinomas, including lung cancer." (PMID 22769244, 2012).
lung carcinoma (continued). "In conclusion, the work reported here supports the development of EGCG as a FASN inhibitor for adenocarcinoma lung cancer treatment." (PMID 22769244, 2012). "Moreover, although inhibiting FASN expression decreases fatty acid levels in non–small-cell lung cancer, it paradoxically increases the ratio of LC3 II to LC3 I, thereby promoting autophagy." (PMID 39567194, 2025). "Interestingly, a recent study has found that the expression of FASN was related to ferroptosis in lung cancer 8, which opens up new horizons in cancer research." (PMID 37283794, 2023). "For example, activation of the TGFβ signaling pathway in lung cancer cells leads to reduced fatty acid synthesis via the inhibition of ChREBP, and knockdown of FASN leads to reduced expression of E-cadherin, which enhanced invasion and metastasis of lung cancer cells." (PMID 36643625, 2023). "In addition, the present study provides a foundation for the design of future clinical trials evaluating the efficacy of targeting SREBP-1/hsa-miR-497-5p SCAP/FASN signaling for the treatment of chemoresistant lung cancer." (PMID 35806291, 2022). "Our results may serve as a reference for the design of future clinical trials of therapeutic modalities that target the SREBP-1/hsa-miR-497-5p/SCAP/FASN oncometabolic signaling axis to overcome chemoresistance in patients with lung cancer." (PMID 35806291, 2022). "Numerous malignancies, including prostate, colon, breast and lung carcinomas, were found to express higher levels of FASN compared with their non-tumor counterparts, and overexpressed FASN was associated with poor prognosis." (PMID 33974005, 2021). "Consistently, FASN inhibition blocks cellular proliferation of KRAS-driven lung cancer cells." (PMID 33194642, 2020). "Indeed, treatment with TGF-β signaling inhibitor SB525334 reverts the FASN (fatty acid synthase)-mediated resistance to NK cell cytotoxicity in cisplatin resistant lung cancer, probably through the modulation of PD-L1 levels on tumor cells." (PMID 31948072, 2020). "Studies performed by 3V- Biosciences have shown an association of FASN inhibitor sensitivity with KRAS mutation status in lung cancer cell lines, but not in analysis of 29 CRC cell lines." (PMID 29872506, 2018). "Moreover, microarray data from Kaplan–Meier plotter (n = 1926) indicated the prognostic role of FASN expression in lung cancer patients (HR = 1.81, 95% CI: 1.47–2.21, adjusted for clinical stage)." (PMID 29722168, 2018). "Improved formulation of Orlistat‐like inhibitors of FASN could represent a promising therapeutic modality in the treatment of lung cancer." (PMID 29449326, 2018). "Moreover, TGFβ/Snail-driven EMT suppresses fatty acid synthase (FASN) expression in lung cancer cells, which is sufficient to stimulate migration and extravasation in vitro, as well as lung metastasis in vivo." (PMID 27586372, 2017). "In this study, we show that adenocarcinoma of lung cancer, is among the foremost of cancers that could potentially be treated by inhibiting FASN." (PMID 22769244, 2012). "In this context, FASN enzyme has became a promising target for anti-cancer therapy, a putative biomarker of malignancy and an indicative of prognosis for many cancers, including lung carcinomas." (PMID 22769244, 2012). "Targeting FASN with C75 in mice leads to pronounced appetite suppression and weight loss, whereas EGCG, due to its lack of significant impact on CPT-1 activity, often does not cause weight loss while inhibiting the growth of adenocarcinoma- and lung carcinoma-derived xenografts." (PMID 41421797, 2025). "However, FASN remodels oxidised phospholipids to escape ferroptosis in KRAS-mutant lung cancer." (PMID 38228715, 2024). "Furthermore, it has been demonstrated that FASN is important for lung cancer cells’ tumorigenesis." (PMID 38069382, 2023). "Consequently, larger sample sizes or clinical features may be required to confirm the role of FASN in different types of lung cancer." (PMID 34879004, 2021).
lung carcinoma (continued). "Previous studies suggests FASN expression is positively correlative with PD-L1 level in cisplatin-resistant lung cancer cells and a human T-cell leukemia line 98, 99, and FASN inhibitor orlistat could suppress cell proliferation and downregulate PD-L1 expression." (PMID 34803494, 2021). "Therefore, our findings supported the hypothesis that circFARSA might contribute to the development of lung cancer by sponging miR‐330‐5p/miR‐326 and relieving their inhibitory effects on oncogene FASN." (PMID 29722168, 2018). "However, a contradictory report stated that FASN knockdown enhanced EMT in lung cancer cells." (PMID 27765901, 2016). "It reflects that in lung cancer cell lines, the activation of MAPK1 (e.g., via arachidonic acid treatment) reduces lipid droplet formation through inhibiting the expression of FASN and proliferator-activated receptor gamma (PPARγ)." (PMID 41010281, 2025). "Previous studies showed that oncogenic KRAS and activated epidermal growth factor receptor (EGFR) promoted FASN expression via ERK in pancreatic and lung cancer cells." (PMID 40621620, 2025). "It upregulates the expression of lipogenic enzymes, such as fatty acid synthase (FASN) and acetyl-CoA carboxylase (ACACA), thus enhancing de novo lipogenesis, resulting in increased lipid droplet formation within lung cancer cells." (PMID 40650139, 2025). "Previous studies indicate a significant correlation between fatty acid synthase (FASN) expression and PD-L1 levels in cisplatin-resistant lung cancer cells and human T-cell leukemia lines." (PMID 40066091, 2025). "The expression levels of lipid metabolism-related enzymes, such as fatty acid synthase (FASN), acetyl-CoA carboxylase (ACC), and acetyl-CoA synthetase (ACSS2), are frequently elevated in lung cancer." (PMID 40657374, 2025). "Even though our report is the first demonstrating that upregulation of FASN increases the expression of GFPT1, other studies have demonstrated the oncogenic role of GFPT1 in cervical cancers, lung cancers and pancreatic cancers." (PMID 38732103, 2024). "We confirmed the results of iTRAQ by western blotting with protein samples from sensitive and resistant brain and lung cancer cells and demonstrated that NCI677397 markedly increased the expression of FDFT1, HMGCS1, FDPS, and FASN." (PMID 38140768, 2024). "For instance, activated enzymes like ACLY, ACC, FASN, and SCD1 were highly expressed in lung cancer tissues, which are correlated with a worse prognosis among patients having NSCLC." (PMID 39323079, 2024). "Aberrantly activated enzymes involved in the metabolism of FAs such as ATP citrate lyase (ACLY), fatty acid synthase (FASN), and acetyl-CoA carboxylase (ACC) in normal cells accelerated cancerous transformation in lung cancer." (PMID 39478862, 2024). "Inhibition of FASN (fatty acid synthase) reduces (SFAs) and (MUFAs), regulating the process of including PUFAs into phospholipids (PLs) of mutant KRAS lung cancer cells, and increasing their sensitivity to ferroptosis." (PMID 38540154, 2024). "However, in A549 and H1975 human lung cancer cell lines, C93 treatment triggered a protective response mediated by NF-kB signaling activation, and the pharmacological inhibition of both NF-kB and FASN led to more effective cell killing than inhibiting either NF-kB or FASN individually." (PMID 35159223, 2022). "Many enzymes in the fatty acid biosynthesis were found upregulated in many lung cancer cells, including the rate-limiting enzymes, ATP citrate lyase (ACLY), acetyl-CoA carboxylase (ACC), fatty acid-synthase (FASN), and phosphatidic acid phosphatase (Lipin1)." (PMID 36293388, 2022). "Mutant KRas upregulates de novo lipogenic genes, including FASN, ACC1, and ACLY, in lung cancer and gemcitabine-resistant pancreatic cancer cells, implying that KRAS-mutant cancer cells are more sensitive to inhibitors of FA synthesis." (PMID 33801246, 2021).